CD4 (CD4 molecule)
Diseases named in the same sentence as CD4 in open-access papers (continued):
Sharing a sentence is not in itself a finding about the gene and the disease.
infection (continued). "Furthermore, endocervical epithelial cells were demonstrated to secrete thymic stromal lymphopoietin (TSLP) in vitro, resulting in the activation of mDC that subsequently produce CCL17 and CCL22, further attracting naive CD4+ T-cells for expansion and infection." (PMID 29415518, 2018). "Additionally, we evaluated the production of IL-17 by CD4+ T cells during infection." (PMID 29675017, 2018). "Finally, since the brain is the primary site of WNV infection and a lower percentage of CD4+ T cells accumulate at this site in infected old mice, we asked if the number of E641-bound cells in the brain on day 10 post-infection was different between adult and old mice." (PMID 29864157, 2018). "At least some of these B. pertussis-specific IFN-γ- and/or IL-17-producing CD4+ T cells that can be found in the mouse lungs after infection may be tissue-resident memory T (Trm) cells, as characterized by the expression of CD44, CD69, and/or CD103 and the lack of expression of CD62L." (PMID 30692990, 2018). "At the site of the infection, interactions between Mtb and antigen-presenting cells, such as alveolar macrophages and dendritic cells, are the initial step of the anti-Mtb responses and lead to the presentation of Mtb antigens to CD4+ and CD8+ T cell in the lymph nodes." (PMID 29520269, 2018). "Furthermore, we identified two kinases not previously reported to have an effect on HIV replication—p70 S6K1 and MK2—that are induced by signaling and required for optimal infection of CD4+ T cells, providing new insights into how HIV manipulates host cells for viral replication." (PMID 29970186, 2018). "Together, these data show that during MCMV infection, the development of a cytotoxic phenotype in CD4 T cells correlates with expression of the transcription factor T-bet and not Eomes, and accordingly IL-27 negatively regulates T-bet expression in CD4 T cells upon infection." (PMID 30044874, 2018). "Moreover, the transmission of HIV-1 from DCs to primary CD4+ T cells may be accomplished via a trypsin-resistant endocytosis mechanisms that leads to a productive infection." (PMID 30364166, 2018). "However, other factors seem to increase the likelihood of infection with opportunistic intestinal protozoa, including CD4 T-lymphocyte counts of less than 100 cells/μl, ingestion of contaminated drinking water or food, exposure to infected pets or animals and unsafe homosexual activity." (PMID 29316950, 2018). "Furthermore, the population of CD25− CD4 T cells was significantly reduced in the peripheral blood of VSVΔG-NP-inoculated mice at 42 dpi, suggesting the population was affected by rVSV infection." (PMID 29212930, 2018). "However, modeling HIV requires more detailed representation of disease progression, such as of CD4 + T cell counts, their depletion during infection, reconstitution during antiretroviral treatment, impact on other infections such as tuberculosis and measurement for clinical decision-making." (PMID 29986020, 2018). "While we were not able to assign statistical significance to SHIV-dependent positive selection in CD4+ subsets, these data suggest that even at low levels, ΔCCR5 HSPCs may give rise to infection-resistant ΔCCR5 CD4+ T-cells that refill the SHIV-depleted CD4+ T-cell niche." (PMID 29672640, 2018). "However, and during the late phase of infection, viral IL-10 is driving infected cells toward M2-like polarization, which may limit virus clearance by restricting proinflammatory and CD4 T cell responses at sites of infection." (PMID 29921749, 2018). "In addition, identification of CD4+ T cells with M protein cross-reactivity lent further insight into mechanisms by which infection may induce an adaptive AAb response via the support of CD4+ T cell help." (PMID 29755478, 2018).
infection (continued). "Therefore, although BACH2 may interact with BLIMP1 to influence CD4+ T cell development and differentiation, our results indicate that this interaction plays a limited role in determining the outcome of infection with P. chabaudi or L. donovani." (PMID 30459773, 2018). "However, SIV from natural hosts can also efficiently use other coreceptors than CCR5 to infect primary CD4+ T cells and other factors might as well be implicated in the relative preservation of TCM to infection in natural hosts." (PMID 29725327, 2018). "However, SeV85AB boosting resulted in a response to infection that contained a higher percentage of Ag85AB-specific poly-functional lung T cells, notably CD4+ T cells with the phenotypes IL-2+TNF-α+/IL-2+, and CD8+ T cells of phenotypes IFN-γ+IL-2+TNF-α+/IL-2+." (PMID 30123219, 2018). "The higher proportion of heterosexual men among undiagnosed with a low CD4 count could depend, partly, on the fact that heterosexuals were more likely to have a longer undiagnosed interval (time lag from infection to HIV diagnosis) as shown in other studies worldwide." (PMID 29667577, 2018). "Thus, we have identified a previously unknown CD4+ ILC1 population that serves as a target for HIV-1 productive infection." (PMID 29304123, 2018). "Thus far, CD4+ T-cell counts and plasma viral load (VL) levels have remained the strongest correlates of progression and are the two markers routinely used in the clinical setting to monitor the infection." (PMID 29342870, 2018). "Thus, CD14+ myeloid cells sorted from infected cervical explants 1 day after infection are more efficient at transmitting infectious HIV to activated CD4+ T cells than cervical CD4 T cells, suggesting an important role of myeloid cell capture early in HIV transmission." (PMID 30532754, 2018). "Inconsistent with this hypothesis, at day 6 post-infection, we did not observe any significant changes to IL-5 and IL-13 mRNA or protein producing CD4 T cells or ILCs in the lungs of infected RELMα-deficient mice during this peak reparative phase." (PMID 30500858, 2018). "In this study, at 2 and 3 weeks post intravenous infection of mice, we also found that all bacteria could induce the activation of CD4+ and CD8+ T lymphocytes, but X4550(pYA3334-P-SspH2-EscI) induced significantly lower level of CD8+T cells activation than X4550(pYA3334-P-SspH2) or X4550(pYA3334)." (PMID 29523140, 2018). "However, gp120 binding to α4β7, like mucosal addressin cellular adhesion molecule (MAdCAM) transduces signals to primary CD4+ T cells, suggesting that such signals may be relevant to infection in vivo." (PMID 30153309, 2018). "Taken together, a reasonable prediction could be that CD4+ T cells should have a reduced responsiveness to immunization or infection in old mice compared with adults even if the mechanistic basis for such impairment may be multi-factorial and challenging to deconvolve." (PMID 29864157, 2018). "Therefore, the presence of LC in the skin could promote a permanent inflammatory environment that preferentially induces the differentiation of CD4+ T cells from the sdLN into effector T cells that are recruited to the site of the infection." (PMID 29946313, 2018). "However, our results show that when the anti-CD4 monoclonal antibody was inoculated into mice, the protection against the infection induced by skin immunization with iC+CT was lost, demonstrating that mainly the circulating memory CD4+ T cells mediate protection against the S. schenckii infection." (PMID 29946313, 2018). "However, key differences between HIV and MV are that the former infects CD4+ T cells and CD4-expressing macrophages and establishes lifelong infection, whereas the latter targets all CD150+ lymphocytes (including CD4+ and CD8+ T cells) and causes acute, self-limiting disease." (PMID 30592772, 2018).
infection (continued). "Also, preexisting immunity from previous infection with related flaviviruses could alter immunodominance patterns of CD4 T cells through cross-reactive memory responses to conserved elements." (PMID 29899743, 2018). "The pathways causing cell death in HIV-infected CD4+ T cells are still not completely elucidated although apoptosis and pyroptosis have been proposed as alternative pivotal mechanisms depending on the outcome of infection." (PMID 30515154, 2018). "Interestingly, the slopes of the lines are distinct for IL-2 (1.51) vs. IFN-γ (2.78) again emphasizing the accumulation of IFN-γ-producing CD4 T cells in the lung, relative to what is detected in the draining LN, where the CD4 T cells are elicited after infection." (PMID 29681900, 2018). "Moreover, the number of CD4+ T cells at the infection sites is increased following HSV-2 infection, which may further facilitate HIV-1 to infect these target cells." (PMID 30619292, 2018). "HIV-1 is expected to penetrate into regions of greater tissue damage with higher probability, where it can encounter high CD4+ T cell concentrations, thus increasing the probability of successful infection above what might be expected if this spatial correlation is not considered." (PMID 29698393, 2018). "Furthermore, in the treated cohort (close to 1000 sera), patients having EC26-2A4ΔM-specific antibodies at early and late stages after infection had a higher CD4 nadir, which according to the US Centers for Disease Control (CDC) determines the clinical stage of HIV infection." (PMID 29662026, 2018). "Furthermore, EVs containing Nef can activate apoptosis of bystander CD4+ T cells, which may also contribute to T cell depletion during infection." (PMID 30364166, 2018). "It has been reported that the V2 loop of HIV-1 gp120 binds to the integrin α4β7 expressed on activated CD4+ T cells, mediating viral uptake and infection, which could be abrogated by anti-V1V2 antibodies, although this may not be applicable for all HIV-1 strains." (PMID 29237847, 2018). "However, more recently IL-27 has also been shown to act as a negative regulator of ongoing immune responses during infection and autoimmune inflammation and under these circumstances IL-27 can limit pro-inflammatory cytokine production by CD4 T cells, including IFNγ." (PMID 30044874, 2018). "Interestingly, a recent study characterizing CD4+ T cell epitopes in P. berghei reported a change in the immunodominance of antigens depending on whether infection was initiated by sporozoites or iRBCs." (PMID 30154793, 2018). "However, PKCa also reduce expression of the HIV entry co-receptors CD4+ and CCR5, which may render cells less susceptible to infection." (PMID 29988382, 2018). "Indeed, deletion of HCV-specific CD4 T cell responses may be the main reason for CD4 T cell failure in chronic HCV-infection." (PMID 30453612, 2018). "Hence, in this study, we investigate the possible association between the infections with HIV and S. japonicum by exploring the alteration of CD4+ and CD8+ T lymphocyte counts and cytokine levels in coinfected individuals compared with those uninfected or infected with HIV or S. japonicum alone." (PMID 30057918, 2018). "CD8+ and CD4+ T cells of the immunized mice were depleted by intraperitoneal injection (4 times) of anti-CD8α and anti-CD4, respectively, at the indicated time points around the infection time point and the effects of such depletion were confirmed after 4 days of the last injection." (PMID 29370185, 2018). "Thus, we identified whether populations of CD4+ T cells and Foxp3+ Tregs within the TC and mLN altered upon infection according to the applied gating strategy (Online Resource 4)." (PMID 29931394, 2018).
infection (continued). "We hypothesized that M. tb-specific CD4+ TSCM are induced by primary infection with M. tb in humans and aimed to determine the kinetics of their generation and to characterize gene expression (GE), homing potential and functional profiles of mycobacteria-specific CD4+ TSCM." (PMID 29545791, 2018). "Our experiments specifically verified that the ability of FVB mice to resist infection with Pneumocystis did not depend on specific T-cell populations that might have compensated for the loss of CD4+ T cells." (PMID 30283457, 2018). "Collectively, these data provide in vivo evidence that neddylation contributes to CD4+ T cell activation, proliferation, and development of optimum Th1 effector response that correlates with better protection against the early acute phase of blood-stage P. yoelii 17XNL infection." (PMID 30462731, 2018). "Since Mφ treated with replication-competent TB40E and UV-TB40E elicited comparable CD4+ T-cell proliferative responses, we concluded that direct presentation of exogenous antigens is constitutively active in Mφ and is not enhanced by inflammatory cytokines released during direct infection." (PMID 29887865, 2018). "Furthermore, there is a significant delay in the appearance of flu-specific TH1 effector CD4+ T cells in the lungs following infection of aged mice, which may contribute to slower viral clearance." (PMID 29616390, 2018). "Thus, we isolated CD4+ T cells from SDLN of infected BALB/c mice 10 days after infection." (PMID 29535708, 2018). "Moreover, CD4+ T cells are crucial helpers to support B cell affinity maturation and generation of parasite-specific immunoglobulin G (IgG), thus contributing to complete elimination of the infection eventually." (PMID 30462731, 2018). "Besides, because the CD4 count may occasionally drop to below 200 cells/mm3 after acute infection, exclusion of patients with a low CD4 count may impact the figures on recent infections." (PMID 29187159, 2017). "The LST reaction reflects a CD4+ Th1 cell-mediated immune response and is a useful indicator of immune status in studies evaluating Leishmania vaccine candidates and an important tool in epidemiological studies to assess exposure to Leishmania and the prevalence of infection." (PMID 29023574, 2017). "Thus, infection appears to be important for inducing PmpG-Tet+ CD4+ T cells that can produce multiple cytokines; IFN-γ, TNF-α, and IL-17 which may only marginally aid in protection from bacterial load in the GT and reproductive tract inflammation." (PMID 28106821, 2017). "The mechanism(s) by which polyfunctional CD4+ T cells induced by vaccines or natural infection may be associated with protection from infection and/or disease have not been defined." (PMID 29051764, 2017). "Indeed, the rapid depletion of gastrointestinal CD4+ T lymphocytes occurring during the early phases of infection leads to a deterioration of the gut epithelium followed by the translocation of microbial products into the systemic circulation and the subsequent activation of innate immunity." (PMID 28661459, 2017). "We postulated that the failure of naïve CD4 T cells and B cells to initiate responses against new specificities could partially be the result of a decline in antigen load following the secondary infection." (PMID 28493882, 2017). "The biological interaction of cyclin F and Vif followed by identification of cyclin F as a negative regulator of Vif and thereby viral infectivity raises the possibility that cyclin F down-regulation during infection in CD4+ T cells could be a virus-mediated effect." (PMID 28184007, 2017). "Furthermore, mDCs that migrate to lymph nodes in response to infection may fuel viral spread by forming conjugates with lymphoid CD4+ T cells." (PMID 28207890, 2017). "However, only little is known whether Yersiniae can directly modulate differentiation of CD4+ T cells, thereby favoring the establishment of infection." (PMID 28378044, 2017).
infection (continued). "Thus, TLR7/8 triggering may have a dichotomous effect in HIV infection by preventing infection of CD4+ T cells while activating HIV expression in others." (PMID 27799218, 2017). "However, given their location at the site of a challenge infection and their rapid production of IFNγ, it might be expected that CD4+ TRM cells may also provide some level of rapid protection that is independent of additional T cell recruitment from the blood." (PMID 28419151, 2017). "We observed that the frequency of naïve CD4+ T cells before infection had a strong inverse correlation with the peak level of exhaustion (PD-1+) CD4+ T cells (r = −0.74, P = 0.0023) and a strong positive correlation with the nadir number of CD4+ T cells (r = 0.86, P < 0.0001)." (PMID 28232735, 2017). "Therefore, taking together, these data suggest that the presence of CD4+ CTL responses at the site of infection may limit virus shedding, replication, and illness severity." (PMID 28289418, 2017). "In contrast, all CD4+IFNγ-/- T cell recipients whether treated with isotype antibody or anti-IL-17A were negative for R. typhi in the organs when the experiment was terminated on day 26 post infection." (PMID 28222146, 2017). "However, Tregs only accounted for approximately 10% of the total IL-10+CD4+ T cells in the uninfected mice and slightly more than 15% of the total IL-10+CD4+ T cells in the infected mice, congruous with an infection-dependent increase in IL-10 production by Foxp3+CD4+ T cells." (PMID 28710387, 2017). "Thus, TNF acts directly on BM CD4+ T cells to regulate their expansion following infection." (PMID 28671989, 2017). "Thus, the C7 TCR was representative of ESAT6-specific CD4+ T cells during infection." (PMID 29176787, 2017). "To investigate whether the observed phenotype of CD4 TEMRA cells specific to DENV was also found for other viruses characterized by multiple rounds of infection, we analyzed CMV- and EBV-specific CD4 TEMRA cells in a cohort of donors that had not been exposed to DENV." (PMID 29133794, 2017). "Furthermore, also the only mouse of the isotype-treated CD4+IFNγ-/- T cell recipient group that died upon infection on day 16 had only very low amounts of bacteria predominantly in the liver (52.0 copies) followed by the brain (20.8 copies), lung (6.49 copies) and spleen (1.01 copies)." (PMID 28222146, 2017). "Collectively, these data suggest that the IL-25 receptor signal is required for ILC2s accumulation during infection, which in turn may enable the capability of CD4+TH effector cells to elicit strong antigen-specific Th2 and Th9 cytokine responses against T. spiralis infection." (PMID 28898280, 2017). "However, the CD4+ T cell subset composition was altered by infection." (PMID 28821806, 2017). "Interestingly, CD4 CTL in seropositive donors co-expressed IL-17 and CD56, two markers not previously associated with cytotoxic CD4 responses in other infections." (PMID 28167943, 2017). "Thus, the direct effect of MPA on infection of CD4+ T cells remains unclear, but is likely affected by multiple factors including dose, time of exposure, cell activation state, and viral strain amongst others." (PMID 29255206, 2017). "Thus, in theory, infection of long-lived macrophages would allow the virus to rapidly evade CD8+ T cell immunity and replicate to produce “escape” mutations that then preferentially infect CD4+ T cells." (PMID 29259605, 2017). "In addition, BALB/c mice infected with C. muris and treated with anti-CD4 monoclonal antibodies had increased duration of patent infection and oocyst shedding, while mice treated with anti-CD8 monoclonal antibodies had only a moderate increase in oocyst shedding." (PMID 29295550, 2017). "Moreover, infection decreased CD4+ and CD8+ T lymphocytes and macrophages of DM mice." (PMID 29091912, 2017).